CALD1 (caldesmon 1)
Description:
Actin- and myosin-binding protein implicated in the regulation of actomyosin interactions in smooth muscle and nonmuscle cells (could act as a bridge between myosin and actin filaments). Stimulates actin binding of tropomyosin which increases the stabilization of actin filament structure. In muscle tissues, inhibits the actomyosin ATPase by binding to F-actin. This inhibition is attenuated by calcium-calmodulin and is potentiated by tropomyosin. Interacts with actin, myosin, two molecules of tropomyosin and with calmodulin. Also plays an essential role during cellular mitosis and receptor capping. Involved in Schwann cell migration during peripheral nerve regeneration (By similarity).
Synonyms: CDM; H-CAD; L-CAD; h-CD; HCAD; LCAD; NAG22
Tractability: Antibody: its Gene Ontology location is reachable by antibodies, with high confidence; the Human Protein Atlas places it where antibodies can reach. PROTAC: UniProt records ubiquitination sites on it; ubiquitination databases record sites on it; its protein half-life has been measured.
Gene: Protein-coding gene on chromosome 7 (134,744,252 to 134,970,729, forward strand). Ensembl gene ENSG00000122786.
Subcellular location: Cytoplasm, cytoskeleton; Cytoplasm, myofibril; Cytoplasm, cytoskeleton, stress fiber
Subcellular location (Human Protein Atlas): Actin filaments; Plasma membrane
Pathways (Reactome):
Muscle contraction: Smooth Muscle Contraction
Gene Ontology:
Molecular function: cadherin binding; protein binding; actin binding; calmodulin binding; myosin binding; tropomyosin binding; cytoskeletal protein binding
Biological process: actin filament bundle assembly; muscle contraction
Cellular component: actin cytoskeleton; plasma membrane; cytoskeleton; cytosol; myofibril; stress fiber
Genetic constraint (gnomAD): Loss-of-function variants: 30 observed, 81.78 expected, observed/expected ratio (o/e) 0.37, 90% interval 0.27 to 0.5. The upper end of that interval is the gene's LOEUF score, 0.5, which puts it in group 2 of 6, group 1 being the genes least tolerant of losing a copy. Missense variants: 760 observed, 861.11 expected, observed/expected ratio (o/e) 0.88, 90% interval 0.83 to 0.94. Synonymous variants: 262 observed, 294.15 expected, observed/expected ratio (o/e) 0.89, 90% interval 0.8 to 0.99.
Homologues: Orthologues: chimpanzee CALD1 (99% identical), macaque CALD1 (98% identical), pig CALD1 (85% identical), guinea pig CALD1 (79% identical), mouse Cald1 (77% identical), rat Cald1 (77% identical), dog CALD1 (75% identical), rabbit CALD1 (60% identical), tropical clawed frog cald1 (59% identical), zebrafish cald1b (30% identical). Paralogues in human: LSP1 (12% identical).
Diseases named in the same sentence as CALD1 in open-access papers:
CALD1 is named in the same sentence as 92 diseases in open-access papers, as found by Europe PMC text mining. Sharing a sentence is not in itself a finding about the gene and the disease. The quoted sentences say what the papers report.
bladder cancer (11 papers, 2020 to 2025). "The expression of CALD1 has been linked to the development of several benign and malignant tumors including uterine leiomyoma, bladder cancer, colon cancer, prostate cancer." (PMID 38365611, 2024). "It has also been reported that CALD1, a key gene associated with cancer-associated fibroblasts, can promote the progression of bladder cancer by remodeling the tumor microenvironment." (PMID 36245970, 2022). "High CALD1 expression was associated with shorter overall survival in bladder cancer." (PMID 36313650, 2022). "In addition, miR-142-5p inhibited CALD1 expression in bladder cancer cells through a direct association, and reversed the proliferation and CALD1 expression in 5,637 cells overexpressing of MIR100HG." (PMID 35127818, 2021). "Being a key gene associated with CAFs, CALD1 may promote bladder cancer progression by remodeling the tumor microenvironment." (PMID 34051818, 2021). "In bladder cancer, CALD1 is a prognostic biomarker and is associated with immune infiltration." (PMID 35127818, 2021). "Further studies have shown that the expression of CALD1 is significantly correlated with immune cell infiltration in bladder cancer, which provides a new perspective for understanding the regulation of the tumor immune microenvironment." (PMID 41181151, 2025). "The results of the analysis showed that seven genes (VCL, FLNA, THBS1, TAGLN, ACTA2, COL6A2, and CALD1) were significantly correlated (P < 0.05) with the prognosis of bladder cancer patients, and these genes were included in the subsequent in-depth study." (PMID 41181151, 2025). "While more studies have identified CALD1 as a prognostic biomarker in bladder cancer, gastric cancer, and colorectal cancer, there is limited research on its role in OC, including its potential involvement in platinum-based chemotherapy resistance." (PMID 38365611, 2024). "MIR100HG/miR-142-5p/CALD1 is an important ceRNA network involved in the occurrence and development of bladder cancer." (PMID 35127818, 2021). "The trends in the expression of MIR100HG and CALD1 were consistent with the transcriptome sequencing results, and their levels were up-regulated in bladder cancer." (PMID 35127818, 2021). "At the same time, the MIR100HG/miR-142-5p/CALD1 axis plays an important role in the progression of bladder cancer." (PMID 35127818, 2021). "Overall, Alterations in the expression of VCL, FLNA, TAGLN, ACTA2, COL6A2, and CALD1 may play important roles in the development of bladder cancer, suggesting their potential value in early detection, molecular subtyping, and targeted therapy." (PMID 41181151, 2025). "Finally, six B-cell marker genes (VCL, FLNA, TAGLN, ACTA2, COL6A2, and CALD1) that were downregulated in bladder cancer were screened using the PPI network, survival curves, ROC curve analysis, and expression validation." (PMID 41181151, 2025). "Recent studies have revealed that CALD1 not only serves as a prognostic biomarker for bladder cancer but may also contribute to its progression of bladder cancer by participating in the remodelling process of the tumor microenvironment." (PMID 41181151, 2025). "Notably, survival prognosis analyses, Cox analysis and additional in silico methods have shown the importance of MIR100HG/miR‐142‐5p/CALD1 axis in bladder cancer development." (PMID 37487022, 2023). "Based on this information, MIR100HG/miR-142-5p may affect the biological processes and staging of bladder cancer by regulating CALD1 expression." (PMID 35127818, 2021). "WGCNA also revealed that CALD1 was a key CAFs-related gene in bladder cancer." (PMID 34051818, 2021). "Moreover, further in-depth analysis showed that CALD1 significantly affected the progression and prognosis of bladder cancer." (PMID 34051818, 2021).
bladder cancer (continued). "Among these identified genes, 5 genes (CALD1, HOXB3, HOXB6, MOGAT2, and TNC) have been reported to be associated with the development or prognosis of bladder cancer, indicating that the results in our study are consistent with previous publications in bladder cancer." (PMID 33204728, 2020). "Mechanistically, miR‐142‐5p can inhibit expression of CALD1 in these cells via a direct interaction and reverses the effects of MIR100HG over‐expression in proliferation of bladder cancer cells." (PMID 37487022, 2023). "Overall, the results from this study indicate that CALD1 is a key gene downstream of the MIR100HG/miR-142-5p axis involved in the initiation and progression of bladder cancer." (PMID 35127818, 2021). "However, our results indicate that CALD1 may be involved in the progression of bladder cancer." (PMID 35127818, 2021). "An experiment in bladder cancer cells has shown that up‐regulation of MIR100HG efficiently promotes proliferation, migration and invasion of the 5637 bladder carcinoma cells, inhibits expression of miR‐142‐5p and induces expression of CALD1." (PMID 37487022, 2023). "CAFs-related genes, such as CALD1 can promote bladder cancer progression by modulating the immunosuppression status of TME and may serve as a prognostic biomarker in bladder cancer." (PMID 36195908, 2022). "In addition, we further found that MIR100HG regulated CALD1 expression by targeting miR-142-5p, and the miR-142-5p mimic reversed the regulatory effect of MIR100HG overexpression on the proliferation of bladder cancer cells." (PMID 35127818, 2021).
gastric cancer (11 papers, 2014 to 2025). A primary or metastatic malignant neoplasm involving the stomach. "CALD1 is a cytoskeleton-associated protein that has been revealed to be related to neoplastic angiogenesis, and immune infiltrates in gastric cancers." (PMID 36599974, 2023). "Since the actin-binding protein caldesmon (CALD1) is a succinylated protein modified at K569 and is associated with metastasis and drug resistance of gastric cancer, it might serve as a critical marker of gastric cancer." (PMID 37777749, 2023). "In gastric cancer models, the high expression of caldesmon 1 (CALD1) further underscores the pivotal role of the PI3K/AKT/mTOR pathway in EMT induction." (PMID 40725100, 2025). "miR-1278 negatively regulates CALD1 expression, affecting the migration of gastric cancer cells by modulating the MAPK pathway." (PMID 38717641, 2024). "Previously, CALD1 acts as a prognostic indicator and also is in relation to immune infiltrates in gastric carcinoma." (PMID 35178409, 2021). "Taking advantage of this site-specific primary antibody, we collected a total of ten pairs of primary human gastric cancer and adjacent normal tissues and detected the level of K569 succinylated CALD1 via western blotting." (PMID 28165029, 2017). "Consequently, these results suggested that the antiproliferative and anti-metastatic impacts of RECK in gastric cancer were CALD1-dependent." (PMID 37904179, 2023). "This study aimed to investigate the interaction between miR-1278 and Caldesmon (CALD1) in gastric cancer (GC) and the regulatory mechanism." (PMID 38025524, 2023). "CALD1 expression correlates positively with immune cells such as CD8+ T cells, CD4+ T cells, macrophages, neutrophils, and others in gastric cancer." (PMID 38717641, 2024). "Concurrently, the mechanism, involving the interplay between ERK1/2 and CALD1, appeared to contribute to the anticancer effects of RECK in gastric cancer." (PMID 37904179, 2023). "The alterations found in CALD1 and CALD1 phosphorylation, which were triggered by RECK, may potentially contribute to the anticancer actions of RECK in gastric cancer cells." (PMID 37904179, 2023).
glioma (11 papers, 2008 to 2025). A benign or malignant brain and spinal cord tumor that arises from glial cells (astrocytes, oligodendrocytes, ependymal cells). "A prior study on glioma neovascularization has also described differential expression of splicing variants of Cald1 in tumour vessels as compared to normal vessels, resulting in upregulation at the protein expression level within the tumour." (PMID 35697697, 2022). "The most significantly mutated genes include FBXW7 (encoding WNT signaling molecule) in B-cell lymphoma, SATB1 (functioning in chromatin remodeling) in T-cell lymphoma, and CALD1 (encoding an actin and myosin binding protein) in glioma." (PMID 34344882, 2021). "Our previous study reveals that CALD1 transcriptomic level in glioma patient-derived tumor cells (GPDCs) associating with glioma grades progression is an accompanying phenomenon." (PMID 34070840, 2021). "Histology and immunofluorescence analysis also indicated that CALD1 associates with vessel architecture, resulting in glioma grade progression." (PMID 34070840, 2021). "The differential expression of splicing variants of CALD1 is closely related to modulation of the glioma vasculature." (PMID 29235490, 2017). "In glioma, microvascular architecture is linked to CALD1 expression levels." (PMID 36654821, 2022). "However, little is known about mechanisms underlying the effect of CALD1 on the microvascular facilitation and architecture in glioma." (PMID 34070840, 2021). "In this work, we investigated the association between l-CALD1 and glioma." (PMID 34070840, 2021). "However, limited information is available on mechanisms underlying the effect of CALD1 on the microvascular facilitation and architecture in glioma." (PMID 34070840, 2021). "Microvascular architecture also associates to l-CALD1 expression levels in glioma." (PMID 34070840, 2021). "However, CALD1 also plays variable regulatory roles in different tumors, such as glioma, where it influences tumor progression by regulating tumor angiogenesis; increased CALD1 expression has been associated with poorer prognosis in GC but with better prognosis in lung cancer." (PMID 38025524, 2023). "Previous studies have found that CALD1 expression is correlated with the prognosis of gastrointestinal and lung cancer and glioma." (PMID 38025524, 2023). "On the other hand, CALD1 is only known to engage in neovascularization and its role in tumor progression, glioma classifications, overall survival, and immunological expression is not well defined." (PMID 36654821, 2022). "Next, potential mechanisms of how CALD1 affected glioma progression were predicted by employing the GO/KEGG enrichment analysis." (PMID 34070840, 2021). "In this study, we explored the role of CALD1 in gliomas by integrating bulk RNA-seq analysis and single cell RNA-seq analysis." (PMID 34070840, 2021). "A positive correlation between CALD1 expression and the gliomas’ pathological grade was noticed, according to the samples from the TCGA and CGGA database." (PMID 34070840, 2021). "Some researchers have indicated that CALD1 expression is restricted to vessel architectures in glioma." (PMID 34070840, 2021). "Increased l-CALD1 expression promoted glioma progression by promoting tumor angiogenesis and immunocytes infiltration." (PMID 34070840, 2021). "Innovatively, this study employed scRNA-seq analysis to reveal the expression of l-CALD1 in gliomas." (PMID 34070840, 2021). "The overall survival analysis based on the LGG GBM cohort (p value < 0.001), the LGG cohort (p value < 0.001) and the GBM cohort (p value < 0.001) suggests that high CALD1 serves as promoter of glioma." (PMID 34070840, 2021). "In order to analyze the role of CALD1 in glioma comprehensively, we selected genes which were calmodulin-dependent proteins differentially expressed in gliomas with different features." (PMID 34070840, 2021).
glioma (continued). "Unfortunately, despite the wealth of information regarding CALD1 activities only in neovascularization, relatively little is known about it in tumor invasion, glioma subtypes, overall survival, and relative immunological activities." (PMID 34070840, 2021). "Considered together, these results indicate that l-CALD1 potentially presents the validation of glioma grading determination." (PMID 34070840, 2021). "CALD1 was found to be remarkably upregulated in neoplastic cells and was involved in tumorigenic processes of gliomas in single cell sequencing analysis." (PMID 34070840, 2021). "Based on the differentially expressed genes around branch point 3, GO enrichment results in BP and MF confirmed that l-CALD1 played a critical role in the angiogenetic process and tumorigenic process of glioma." (PMID 34070840, 2021). "Further, the expression level of l-CALD1 was explored in the tumor microenvironment of glioma via single-cell sequencing analysis." (PMID 34070840, 2021). "High expressions of CALD1, CALML4, CALML6, CALM1 and CALM2 were associated with IDH wildtype glioma." (PMID 34070840, 2021). "The purpose of this study was to explore the role of CALD1 for prediction glioma patient prognosis and in glioma angiogenesis." (PMID 34070840, 2021). "The CALD1 differential exon inclusion event was present predominantly in glioma cell lines and GBM patient samples." (PMID 18474104, 2008). "CALD1 has been shown to regulate glioma progression by promoting tumour angiogenesis." (PMID 40365337, 2025). "The identification of l-CALD1 expression levels might be useful not only in guiding clinical diagnosis but also in tracking the progression of glioma." (PMID 36654821, 2022). "l-CALD1 is also considered as a potential serum marker for glioma." (PMID 34070840, 2021). "Moreover, KEGG enrichment analysis showed that CALD1 was involved in tumorigenic processes of gliomas." (PMID 34070840, 2021). "Biofunction prediction suggested that CALD1 may affect glioma progression through modulating tumor angiogenesis." (PMID 34070840, 2021). "Biofunction prediction suggested that CALD1 may affect gliomas progression through modulating tumor angiogenesis." (PMID 34070840, 2021). "In conclusion, the present study implies that CALD1 may serve as putative marker monitoring the progress of glioma." (PMID 34070840, 2021). "The expression of CALD1 in gliomas was further investigated via single cell sequencing analysis." (PMID 34070840, 2021). "l-CALD1 was also considered a potential serum marker for glioma." (PMID 34070840, 2021). "In addition, high CI (calmodulin index) predicted worse prognosis in glioma, and furthermore, CALD1 may serve as a key marker for monitoring the progress of glioma and a novel target for therapy." (PMID 34070840, 2021). "This analysis confirmed significantly upregulation of LRGs score and its core genes (KIF2C, CALD1, HSPE1, and IFI16) in glioma versus normal tissues." (PMID 41035644, 2025). "Results from both the TCGA and CGGA dataset suggest that the expression of CALD1, CALML4 and CALML6 was higher in WHO grade III glioma than WHO grade II glioma." (PMID 34070840, 2021). "Low CALD1 expression indicates worse survival outcome both in the MGMT methylated (p value < 0.001) and MGMT unmethylated (p value < 0.001) glioma." (PMID 34070840, 2021). "The current study suggests that l-CALD1 could imply abnormal microvessels in anaplastic astrocytoma and GBM, it recognizes high CI as an unfavorable feature of glioma, and find that CALD1 could serve as putative marker monitoring the progress of glioma." (PMID 34070840, 2021). "CALD1 expression was increased in high grade glioma, IDH wildtype glioma, 1p19q non-codeletion glioma, MGMT unmethylated glioma and aggressive subtype glioma." (PMID 34070840, 2021). "However, the functional role and underlying mechanism of SMOC1, HIPK2, UBA52, S100A6, PPP1CB, CALD1, and TMSB4X in the occurrence and development of diffuse high-grade gliomas was still unknown." (PMID 39530009, 2024).
glioma (continued). "However, in the CGGA dataset, only CALD1, CALML4 and CALML6 were associated with IDH wildtype glioma, and no specific relationship with CALM3, CALM1 and CALM2 expression was noticed." (PMID 34070840, 2021). "CALD1, CALML4 and CALML6 might serve as unfavorable biomarkers in glioma." (PMID 34070840, 2021).